HDAC11 (histone deacetylase 11)
Description:
Responsible for the deacetylation of lysine residues on the N-terminal part of the core histones (H2A, H2B, H3 and H4). Histone deacetylation gives a tag for epigenetic repression and plays an important role in transcriptional regulation, cell cycle progression and developmental events. Histone deacetylases act via the formation of large multiprotein complexes.
Synonyms: HD11
Tractability: Small molecule: an approved drug acts on it; a high-quality ligand is known; it belongs to a druggable protein family. Antibody: its Gene Ontology location is reachable by antibodies, with high confidence. PROTAC: ubiquitination databases record sites on it; a small molecule that binds it is known. Other modalities: an approved drug acts on it.
Target class: Eraser; HDAC class IV; Epigenetic regulator; Histone deacetylase
Gene: Protein-coding gene on chromosome 3 (13,479,724 to 13,506,424, forward strand). Ensembl gene ENSG00000163517.
Subcellular location: Nucleus
Subcellular location (Human Protein Atlas): Nucleoplasm; Cytosol
Pathways (Reactome):
Disease: Constitutive Signaling by NOTCH1 HD+PEST Domain Mutants; Constitutive Signaling by NOTCH1 PEST Domain Mutants
Developmental Biology: Differentiation of naive CD4+ T cells to T helper 2 cells (Th2 cells)
Gene expression (Transcription): Notch-HLH transcription pathway
Signal Transduction: NOTCH1 Intracellular Domain Regulates Transcription
Gene Ontology:
Molecular function: histone deacetylase activity, hydrolytic mechanism; protein binding; DNA-binding transcription factor binding; histone deacetylase activity
Biological process: chromatin organization; chromatin remodeling
Cellular component: histone deacetylase complex; nucleoplasm; nucleus; plasma membrane
Genetic constraint (gnomAD): Loss-of-function variants: 21 observed, 37.51 expected, observed/expected ratio (o/e) 0.56, 90% interval 0.4 to 0.81. The upper end of that interval is the gene's LOEUF score, 0.81, which puts it in group 3 of 6, group 1 being the genes least tolerant of losing a copy. Missense variants: 394 observed, 474.74 expected, observed/expected ratio (o/e) 0.83, 90% interval 0.76 to 0.9. Synonymous variants: 184 observed, 188 expected, observed/expected ratio (o/e) 0.98, 90% interval 0.87 to 1.11.
Homologues: Orthologues: macaque HDAC11 (99% identical), chimpanzee HDAC11 (97% identical), pig HDAC11 (94% identical), mouse Hdac11 (92% identical), guinea pig HDAC11 (92% identical), rabbit HDAC11 (91% identical), rat Hdac11 (91% identical), zebrafish hdac11 (74% identical), tropical clawed frog hdac11 (63% identical), dog HDAC11 (59% identical), Drosophila melanogaster HDAC11 (49% identical), Caenorhabditis elegans hda-11 (44% identical). Paralogues in human: HDAC4 (30% identical), HDAC9 (30% identical), HDAC5 (29% identical), HDAC7 (26% identical), HDAC1 (22% identical), HDAC6 (22% identical), HDAC2 (22% identical), HDAC3 (22% identical), HDAC8 (18% identical), HDAC10 (11% identical).
Diseases named in the same sentence as HDAC11 in open-access papers:
HDAC11 is named in the same sentence as 99 diseases in open-access papers, as found by Europe PMC text mining. Sharing a sentence is not in itself a finding about the gene and the disease. The quoted sentences say what the papers report.
breast cancer (17 papers, 2015 to 2025). A primary or metastatic malignant neoplasm involving the breast. "However, a low HDAC11 level may still contribute to the invasiveness of malignant cells: low levels of this HDAC have been reported to increase the risk of metastasis in breast cancer." (PMID 34439300, 2021). "Nevertheless, another study showed using mouse models that HDAC11 facilitates the growth of breast cancer lymph node metastases while inhibiting the migration from lymph node to distant organs." (PMID 40165290, 2025). "Mocetinostat, an inhibitor of HDAC1-3 and HDAC11, induced the expression of tumor suppressor Fyn-related kinase in basal-like breast cancer and showed antitumor effects in those overexpressing HDAC2." (PMID 40165290, 2025). "HDAC11 expression, in contrast, was correlated with better overall survival of breast cancer patients, and HDAC11 knockdown led to enhanced proliferation, migration, and invasion of breast cancer cells in vitro." (PMID 40165290, 2025). "For example, HDAC11 has been shown to promote hypoacetylation of E2F, a transcription factor that drives cell cycle progression in breast cancer cells." (PMID 41275091, 2025). "In contrast, in basal-like breast cancer (BLBC), HDAC11 expression is downregulated, and overexpression of HDAC11 can suppress in vitro invasion and in vivo metastasis in xenograft breast cancer models, such as the SUM1315 and BT549 cell lines." (PMID 39620228, 2024). "Its overexpression in various cancers, including hepatocellular, ovarian, myeloma, lymphoma, and breast cancers, has suggested HDAC11 is an epigenetic regulator in human cancers." (PMID 38536720, 2024). "HDAC11 is overexpressed in certain cancer cell lines, including prostatic (PC-3), ovarian (SK-OV-3), and breast cancer (MCF-7) cells, and HDAC11 inhibition has shown beneficial effects in neuroblastoma cells and Hodgkin lymphoma." (PMID 38536720, 2024). "Although most studies on the function of HDAC11 suggest an oncogenic role, as in breast cancer the downregulation of HDAC11 provided the cells with an increased ability to invade from the lymph nodes to other organs." (PMID 33316946, 2020). "Chromatin modifier, HDAC11, regulates lymph node metastasis development and dissemination in the breast cancer experimental model." (PMID 32719718, 2020). "Collectively, we reveal a mechanism explaining how HDAC11 plasticity promotes breast cancer growth as well as dissemination from LNs and suggest caution with the use of HDAC inhibitors." (PMID 31519896, 2019). "High expression of HDAC11 has been found in several different solid tumors, including breast carcinoma, hepatocellular carcinoma, and renal carcinoma." (PMID 25915736, 2015). "However, a recent study indicated that down-regulation of HDAC11 would promote tumor metastasis from lymph nodes in breast cancer." (PMID 35252174, 2022). "Furthermore, it was demonstrated that HDAC11 promotes breast cancer growth and dissemination from lymph nodes (LNs) through activation of PRM2 (pro-metastatic) and inhibition of E2F7 and E2F8 (cell cycle suppressors)." (PMID 36076918, 2022). "Moreover, prior research noted that HDAC11 was a novel prognostic marker, affecting apoptosis and maintaining the metabolism and viability of cancer cells in prostate cancer, pancreatic cancer, ovarian and breast cancer." (PMID 34308568, 2021). "Moreover, over-expression of human HDAC11 in MDA-MB-231 breast cancer or 293 T cell lines, resulted in significant enrichment of the promoter regions of these genes by chromatin immunoprecipitation-qPCR (ChIP-qPCR) when probing for HDAC11." (PMID 31519896, 2019). "In support of decreased HDAC11 within LNs leading to increased RRM2 and distant metastasis, functioning as a “release mechanism,” we found that RRM2 is highly associated with poor disease-free survival in breast cancer, including patients with LN involvement at diagnosis." (PMID 31519896, 2019).
breast cancer (continued). "However, inhibition of HDAC11 in animal models of breast cancer increases metastatic dissemination, hypothesized to be due to increased expression of the pro-migratory protein ribonucleotide reductase M2 in breast cancer cells." (PMID 40943415, 2025). "Relatively, M344 may be a poor inhibitor of HDAC11 (18% inhibition at 100 μΜ in HEK293) in comparison to vorinostat, which significantly upregulated HDAC11-target genes in breast cancer cells at 0.5 μΜ." (PMID 40943415, 2025). "In basal-like breast cancer cells with decreased HDAC11 expression, overexpression of HDAC11 did not inhibit tumor growth but did inhibit invasion and metastasis." (PMID 38536720, 2024). "In addition, a KM plot analysis of breast cancer patients (n=500, HER negative) from GSE25066 showed that patients with low HDAC11 expression had significantly shorter survival times than patients with high HDAC11 expression after chemotherapy." (PMID 38536720, 2024).
colorectal cancer (14 papers, 2018 to 2025). A primary or metastatic malignant neoplasm that affects the colon or rectum. "Firstly, our data underline the actual expression pattern of HDAC11 in colorectal cancer." (PMID 35399729, 2022). "To explore whether the alteration of Mmp3 expression plays a critical role in HDAC11- mediated inhibition of colorectal cancer cell migration and invasion, we designed vectors encoding mouse Mmp3 and reintroduced it into CT26.WT cells." (PMID 35399729, 2022). "Colorectal cancer-derived EVs promoted the macrophage polarization of toward M2 by inhibiting histone deacetylase 11 (HDAC11) expression." (PMID 40443670, 2025). "In colorectal cancer, HDAC11 downregulates MMP3 expression by reducing histone H3K9 acetylation at the MMP promoter, thereby suppressing colorectal cancer metastasis." (PMID 38374872, 2024). "For instance, in colorectal cancer, this polarization occurs via the down-modulation of histone deacetylase 11 mediated by miR-145 within colorectal cancer cell-derived EVs." (PMID 39698297, 2023). "In our system, HDAC11 overexpression had a remarkable impact on migration and invasion abilities of colorectal cancer cells." (PMID 35399729, 2022). "We also found HDAC11 inhibits the migration and invasion of colorectal cancer cell by downregulating Mmp3 expression." (PMID 35399729, 2022). "And HDAC11 is downregulated in the relative high metastatic potential colorectal cancer cells compared to the relative low metastatic potential colorectal cancer cells." (PMID 35399729, 2022). "In conclusion, our data suggest HDAC11 as a potential novel target for controlling the invasion and metastasis of colorectal cancer." (PMID 35399729, 2022). "In this study, we show that HDAC11 is downregulated in colitis-associated cancer (CAC) mouse model and human patients with colorectal cancer and inversely related to lymph node metastasis." (PMID 35399729, 2022). "Accordingly, we transiently transfected mouse CT26.WT colorectal cancer cells, which have high invasive and metastatic potential, with plasmids containing Hdac11 cDNA and siRNAs targeting Hdac11." (PMID 35399729, 2022). "Clinically HDAC11 expression is significantly lower in colorectal cancer tissues of patients and correlated with lymph node metastasis." (PMID 35399729, 2022). "In the 103 individuals with colorectal carcinoma, the HDAC11 level inversely correlated with clinical stage, and lymph node metastasis (P=0.029 and 0.029, respectively)." (PMID 35399729, 2022). "Secondly, these studies also provide important insights into the role of HDAC11 in colorectal carcinoma invasion and metastasis." (PMID 35399729, 2022). "Exosomal miR-145 from colorectal cancer cells induces the M2 polarization of macrophages by decreasing the expression of histone deacetylase 11 (HDAC11)." (PMID 32595638, 2020). "Additionally, miR-145 secreted from colorectal cancer cells via EVs is taken up by macrophages where it promotes polarization to the M2-like phenotype through the downregulation of histone deacetylase 11 (HDAC11)." (PMID 36670988, 2023). "Additionally, HDAC11 is downregulated in the relative high metastatic potential colorectal cancer cells." (PMID 35399729, 2022). "Through a better understanding of this previously unknown role of HDAC11 in migration and invasion of colorectal cancer, HDAC11 may become a novel candidate for developing rational therapeutic strategies." (PMID 35399729, 2022). "Additionally, we find a novel mechanism that HDAC11 inhibits colorectal cancer cell migration and invasion by down-regulating Mmp3 expression in vitro." (PMID 35399729, 2022). "In addition, clinically HDAC11 expression is obviously downregulated in colorectal cancer specimens with lymph node metastasis." (PMID 35399729, 2022). "Our studies identify a role for HDAC11 first as a suppressor of colorectal cancer metastasis." (PMID 35399729, 2022). "Above results indicated that HDAC11 could play pivotal roles in the development of colorectal cancer." (PMID 35399729, 2022).
colorectal cancer (continued). "In addition, uptake of EVs enriched with miR-145 derived from colorectal cancer cells by macrophages increases their oncogenic effects via downregulation of histone deacetylase 11 (HDAC11)." (PMID 32992449, 2020). "Moreover, colorectal cancer EVs containing miR-145 polarize macrophages to the M2 phenotype through downregulation of histone deacetylase 11 (HDAC11)." (PMID 31766495, 2019). "The authors found that miR-145 secreted by colorectal cancer cells via MVs is taken up by TAMs, targets histone deacetylase 11 (HDAC11) and TLR4, enhances the production of IL-10, promotes the polarization of TAMs to M2-like macrophages, and promotes tumor progression." (PMID 30443251, 2018). "Our data indicate that HDAC11 may be a metastasis suppressor in colorectal cancer." (PMID 35399729, 2022). "However, few researches focused on the actual expression patterns of HDAC11 in colorectal cancer." (PMID 35399729, 2022). "In the study, the authors found that HDAC11, a member of the histone deacetylase (HDAC) family, is downregulated in human colorectal cancer (CRC) tissues." (PMID 37511338, 2023). "We extracted the cellular proteins of colorectal cancer cell lines SW620 and SW480, and detected the expression of HDAC11 by Western blotting." (PMID 35399729, 2022). "The negative correlation between HDAC11 and lymph node metastasis that we found in colorectal cancer clinical specimens impelled us to explore whether HDAC11 plays a role in regulation of malignant biological behaviors of colorectal cancer cells, including migration, invasion and metastasis." (PMID 35399729, 2022).
glioma (11 papers, 2008 to 2024). A benign or malignant brain and spinal cord tumor that arises from glial cells (astrocytes, oligodendrocytes, ependymal cells). "However, HDAC11 expression is negatively correlated with high-risk uveal melanomas and gliomas, and HDAC11 knockout mice demonstrate increased tumor growth, indicating that its regulation of different cancer types is complex." (PMID 38536720, 2024). "However, HDAC11 expression is inversely correlated with high-risk uveal melanomas and gliomas, and HDAC11 knockout mice have increased lymphoma tumor growth." (PMID 38536720, 2024). "On the contrary, HDAC11 (p = 3.74e−12) expression was negatively associated with glioma grade." (PMID 34540896, 2021). "Univariate Cox regression indicated that high expression levels of HDAC1, HDAC3, HDAC7 and HDAC9 were associated with poor OS of glioma, and elevated expression levels of HDAC4, HDAC5, HDAC6 and HDAC11 were associated with a favorable prognosis of glioma." (PMID 35545840, 2022). "Differentially expressed HDAC family members were identified with significance in ONCOMINE, namely the upregulated HDAC1 and HDAC6, as well as the downregulated HDAC4, HDAC5, and HDAC11 in glioma." (PMID 34540896, 2021). "The HDAC1 and HDAC2 comparisons in glioma, and the HDAC11 comparison in GBM, were remarkable for their significantly contrasting expression." (PMID 34540896, 2021). "Considering the findings from ONCOMINE, GEPIA, and CGGA, HDAC1, HDAC2, and HDAC11 were thus verified for their differential expression in glioma." (PMID 34540896, 2021). "In contrast, under-expressed HDAC4, HDAC5, and HDAC11 ranking within the top 1% gene rank were observed in glioma." (PMID 34540896, 2021). "Other clusters with positively co-correlated genes containedPPARGC1B and HDAC11, both strongly down-regulated in gliomas, and HDAC2, HDAC9 andSIRT6." (PMID 25791281, 2015). "The same significant difference for low-grade and high-grade gliomas was observed for HDAC11 (class IV)." (PMID 18713462, 2008). "In our study, we also found high levels of HDAC11 in normal brain tissue and significant differential expression was also observed for this enzyme in low-grade and high-grade gliomas." (PMID 18713462, 2008). "In addition, HDAC11, which was negatively correlated with the expression of NUP205, was found to have low expression in glioma tissue and was associated with a better prognosis in glioma patients." (PMID 37284202, 2023). "HDAC11 expression was lower in glioma tumor than in normal tissues." (PMID 35359455, 2022). "High HDCA1 and low HDAC11 mRNA expression levels were significantly related to glioma OS and DFS." (PMID 35359455, 2022). "We first performed the univariate cox regression and found that the elevated expressions of HDAC7, HDAC3, and HDAC1 were associated with poor prognosis while increased expressions of HDAC6, HDAC5, HDAC4, and HDAC11 were favorable for prognosis in low-grade glioma." (PMID 36227941, 2022). "In addition, we found that HDAC11 expression levels correlatedsignificantly with the survival time of patients with gliomas (all tumor samplescombined)." (PMID 25791281, 2015). "HDAC11 downregulation was significantly correlated with tumor stage, poor OS, and DFS in patients with glioma." (PMID 35359455, 2022). "In contrast to less efficient discrimination of HDAC2 and HDAC11, the AUC value of HDAC1 over 0.7 throughout the time points manifested that HDAC1 was identified to be a promising prognostic biomarker for glioma." (PMID 34540896, 2021). "Among all patients studied,the expression of HDAC1 and HDAC3 was inversely correlated withsurvival, whereas the expression of HDAC4, HDAC5, HDAC6,HDAC11 and SIRT1 was significantly and positively correlated withsurvival time of patients with gliomas." (PMID 25791281, 2015).
glioma (continued). "We also identified that HDAC1 and HDAC3expression levels were negatively correlated with survival time among gliomapatients, whereas the expression of HDAC4, HDAC5, HDAC6,HDAC11 and SIRT1 was positively correlated with survival time ofpatients with gliomas." (PMID 25791281, 2015).